CASP1 (caspase 1)
Diseases named in the same sentence as CASP1 in open-access papers (continued):
Sharing a sentence is not in itself a finding about the gene and the disease.
influenza (12 papers, 2012 to 2024). An acute viral infection of the respiratory tract, occurring in isolated cases, in epidemics, or in pandemics; it is caused by serologically different strains of viruses (influenzaviruses) designated A, B, and C, has a 3-day incubation period, and usually lasts for 3 to 10 days. "Increased mortality, massive cellular infiltration, and elevated NO production have been observed in Il18−/− mice infected with influenza A; with increased susceptibility to influenza reported for Nlrp3−/− and Casp1−/− mice." (PMID 35822051, 2021). "Simultaneous activation of multiple cell death pathways involving RIPK3 and caspase-8/caspase-1 is proposed to occur during infection by a number of pathogens including Legionella, Francisella, influenza, and Yersinia." (PMID 39058785, 2024). "The NLRP3 inflammasome is a multiprotein intracellular complex comprising NLRP3, ASC, and pro-caspase-1 that is activated upon infection with influenza, as well as other RNA viruses." (PMID 36558964, 2022). "Accordingly, the markedly reduced levels of cleaved caspase-1 in the lungs of influenza-infected mice after neutrophil depletion is indicative of the absence of the second signal driving inflammasome activation and IL-1β release." (PMID 29079611, 2018). "Finally, we assessed the role of caspase-1/11 in the generation of the adaptive immunity in response to vaccination with an IQB90 adjuvanted-influenza vaccine in mice." (PMID 34835281, 2021). "Caspase-1 also plays a role in IgG production during influenza infection." (PMID 29891920, 2018). "A recent paper showed that DCs from elderly mice exhibited decreased expression of ASC, NLRP3, and caspase-1 compared with DCs from infected young mice and the concomitant blunted IL-1β response resulted in enhanced morbidity and mortality in influenza-infected elderly mice." (PMID 24409181, 2013). "Combined stimulation with influenza and R848 resulted in markedly increased production of pro-IL-1β (153.9%, p = 2.22 × 10−16) and IL-1β (339.8%, p = 2.22 × 10−16), with more moderate but significant increases in caspase-1 (32.0%, p = 0.009) and IL-18 (8.5%, p = 2 × 10−5)." (PMID 35822051, 2021). "Interestingly, the magnitude of caspase-1 (p = 0.012) and IL-18 (p = 0.024) production in response to influenza + R848 was greater at Day 1 compared to baseline, while the opposite was true for IL-1β (p = 0.031) and pro-IL-1β (p = 0.024) secretion in response to influenza alone." (PMID 35822051, 2021). "It is well known that IL-1 cytokines are crucial to the Th1 and CD8+ T cell adaptive immune response to influenza; accordingly, ASC and caspase-1 are also needed for protective adaptive immunity." (PMID 24409181, 2013). "Following murine infection with influenza, aged DC show impairments in NLRP3 inflammasome/caspase-1 activation, and downstream IL-1β and IL-18 production, suggesting age-related impairments in DC pathogen sensing and/or innate activation." (PMID 22862959, 2012). "To determine whether IFN-γ and TNF mediate the observed inflammasome activation, we treated aged-influenza infected mice with neutralizing antibodies against both IFN-γ and TNF starting 21dpi and observed a decrease in caspase-1 activity." (PMID 38077031, 2023). "Conversely, the second signal driving inflammasome activation and IL-1β release is lacking, with levels of cleaved caspase-1 (generated through inflammasome activation) markedly reduced in the lungs of influenza-infected mice after neutrophil depletion." (PMID 29079611, 2018). "Notably, unlike WT Mx1 mice, caspase-1/11 KO Mx1 mice were spared from influenza disease exacerbation even when preconditioned in low ambient humidity of 10% RH." (PMID 31085641, 2019). "A requirement for ASC, but not NLRP3 or caspase-1, was also demonstrated for antigen-specific humoral immunity after vaccination with MF59-adjuvented influenza." (PMID 32366256, 2020).
myocarditis (12 papers, 2018 to 2025). Myocarditis is a condition that is characterized by inflammation of the heart muscle (myocardium). "Accordingly, an in vivo model of Coxsackie virus B3 (CVB3)-induced myocarditis demonstrated a significant increase in the inflammasome components caspase-1 and apoptosis-associated speck-like protein containing a caspase-1 recruiting domain (ASC)." (PMID 40146392, 2025). "In mice, pharmacologic inhibition or genetic deletion of cathepsin B markedly reduced caspase-1 activation and IL-1β release in the heart, thereby attenuating myocarditis severity." (PMID 40832143, 2025). "Post-infarction myocardial inflammation was characterized by increased Asc and Nlrp3 gene expression and caspase-1, IL-1β, and Nlrc4 protein expression." (PMID 40332346, 2025). "Previously we reported that CD11b, TLR4, caspase-1, and IL-1β were increased by testosterone in male mice with myocarditis." (PMID 36741845, 2022). "In contrast, animals infected with strains that show low virulence showed slight enhancement of NLRP3, caspase-1, IL-1β and discreet myocarditis." (PMID 34336720, 2021). "It has been verified that inhibiting inflammasome activation by treating mice with caspase-1 inhibitor significantly alleviated CVB3-induced myocarditis." (PMID 29360865, 2018). "In terms of diagnosis, endomyocardial biopsy showing active caspase-1 or GSDMD pores could help confirm myocarditis and distinguish it from ischaemic injury." (PMID 40832143, 2025). "Consistent with observations in endomyocardial biopsies from patients with ICI-induced myocarditis, we observed increased GBP5 protein expression and CASP-1 cleavage following cytokine treatment." (PMID 40940808, 2025). "On the other hand, the high virulent T. cruzi strains induce the upregulation of NLRP3, caspase-1, IL-1β, TNF-α, and iNOS mRNA in heart muscle, compared to low and medium virulent strains, which may contribute to myocarditis and death." (PMID 34336720, 2021). "In this study we found that exposure to BPA in drinking water elevated proinflammatory cytokines/ receptors in the heart of female mice during CVB3 myocarditis that would typically be elevated in male mice or men with mycarditis such as TLR4, caspase-1, IL-1β, IL-17A, and IFNγ." (PMID 31551929, 2019).
silicosis (12 papers, 2011 to 2026). Silicosis is a respiratory disease caused by breathing in (inhaling) silica dust. "As previously shown, the deficiency of Nlrp3/Caspase-1/Gsdmd pathway cannot block silicosis, suggesting that IL-1β has a more fundamental role in silicosis." (PMID 36459518, 2022). "NLRP3 and its downstream factors, caspase-1, IL-1β, and IL-18, were greatly expressed in the lung tissue of rats with silicosis, while the inhibition or deficiency of NLRP3 alleviated EMT in lung epithelial cells or inflammation in macrophages." (PMID 34360876, 2021). "We found 2 SNPs (Ex4-849C>T in Nalp3 and Ex2+37G>A in caspase-1) that were significantly associated with an increased risk of silicosis." (PMID 26496436, 2015). "In conclusion, we found 2 SNPs (Ex4-849C>T of Nalp3 and Ex2+37G>A of caspase-1) that are associated with an increased risk of silicosis in a Chinese population." (PMID 26496436, 2015). "In the present study, we evaluated the relationship between the Ex2+37G>A polymorphism in caspase-1 and the risk of silicosis in Chinese iron miners." (PMID 26496436, 2015). "In this case-control study, 5 SNPs in Nalp3, IL-1β, and caspase-1 genes were evaluated to define the risk of silicosis in a Chinese population." (PMID 26496436, 2015). "Our results showed that the minor allele A of Ex2+37G>A in caspase-1 was associated with a significantly increased risk of silicosis." (PMID 26496436, 2015). "After adjusting for age, smoking status, and CDE, the frequency of the GA genotype for the Ex2+37G>A polymorphism in caspase-1 was significantly higher among silicosis cases than controls (OR [95%CI] = 3.62 [1.63–8.02])." (PMID 26496436, 2015). "Among subjects aged 70 years and older, those with the CT genotype of Ex4-849C>T in Nalp3 and those with the GA genotype of Ex2+37G>A in caspase-1 had a higher risk of silicosis than those with other genotypes (adjusted ORs [95%CI] = 2.52[1.04–6.12] and 5.19[1.88–14.35], respectively)." (PMID 26496436, 2015). "In order to investigate the interactions of genetic polymorphisms of Nalp3, caspase-1, and IL-1β with occupational dust exposure and the joint effects on the risk of silicosis, we conducted a case-control study of a large cohort of workers in a large iron mine." (PMID 26496436, 2015). "Stratification analysis for associations between genotypes of caspase-1 and the risk of silicosis." (PMID 26496436, 2015). "Genetic polymorphisms in Nalp3 and caspase-1 may be associated with individual susceptibility to silicosis, especially when the polymorphisms interact with age, CDE, or smoking status." (PMID 26496436, 2015). "Among subjects with CDE greater than 120 mg/m3×year and among smokers, those with the GA genotype of Ex2+37G>A in caspase-1 had a higher risk of silicosis than those with other genotypes (adjusted ORs[95%CIs] = 26.37[3.35–207.39] and 3.47[1.40–8.64], respectively)." (PMID 26496436, 2015). "Therefore, we hypothesized that genetic polymorphisms in Nalp3, caspase-1, and IL-1β may affect an individual’s susceptibility to silicosis." (PMID 26496436, 2015). "In vivo studies further validated that XFBD significantly downregulates the expression of NLRP3 and Cleaved-Caspase-1 proteins in the lung tissues of mice afflicted with silicosis." (PMID 41754797, 2026). "For example, in silicosis, caspase-1-mediated cleavage of gasdermin D (GSDMD) and caspase-3/8-mediated cleavage of gasdermin E (GSDME) drive pyroptotic cell death." (PMID 40384344, 2025). "Taken together, these data demonstrated that Caspase-1/Gsdmd and Caspase-8/Gsdme both mediated IL-1β maturation and secretion in silicosis." (PMID 36459518, 2022). "This study highlights that Caspase-1/Gsdmd and Caspase-3/8/Gsdme-dependent pyroptosis is essential for the development of silicosis, implicating new potential targets and drug for silicosis treatment." (PMID 36459518, 2022).
silicosis (continued). "To evaluate the physiological relevance of Gsdmd, Gsdme and silicosis, we established experimental silicosis mouse model for WT, Nlrp3-/-, Caspase-1-/-, Gsdmd-/-, Gsdme-/- and Gsdmd-/-Gsdme-/- mice." (PMID 36459518, 2022). "BMSC treatment attenuated NLRP3 and caspase-1 expression, relieving lung inflammatory infiltrates and collagen deposition effectively in the silicosis rat model." (PMID 34360876, 2021). "After adjusting for age, smoking status, and CDE, subjects with the CT genotype of Ex4-849C>T in Nalp3 and the GA genotype of Ex2+37G>A in caspase-1 had increased risks of silicosis (adjusted ORs[95%CIs] = 2.40 [1.12–5.12] and 3.62 [1.63–8.02], respectively)." (PMID 26496436, 2015). "Furthermore, we found that in addition to Caspase 1, Caspase-8 cleaved IL-1β in silicosis, explaining why Caspase-1-/- mice also suffered from silicosis." (PMID 36459518, 2022). "To test whether tetracycline ameliorates caspase-1 dependent pulmonary inflammation in acute silicosis, we challenged C57Bl/6 J mice i.t. with silica particles and treated them with tetracycline." (PMID 35130879, 2022). "To investigate whether tetracycline is a therapeutic option to block inflammasome-caspase-1 driven inflammation in silicosis, we incubated macrophages with silica alone or combined with tetracycline." (PMID 35130879, 2022). "NALP3 (NACHT, LRR and PYD domains-containing protein 3) inflammasome components, caspase-1 and IL-1β, are also required for silicosis and our preliminary findings indicate that caspase-1 is required for autoantibody induction (Kono and Pollard, unpublished observations)." (PMID 23557436, 2013). "Activated Caspase-1 triggers the cleavage of proinflammatory cytokines, interleukin 1-beta and interleukin 18 for subsequent activation and secretion, which is likely to be part of the pathway leading to silicosis." (PMID 21311600, 2011). "Therefore, there exists a compensatory mechanism in which Caspase-8 mediates IL-1β maturation in the absence of Caspase-1 activity, explaining why Caspase-1 deficiency failed to protect mice from silicosis." (PMID 36459518, 2022). "There is no increased caspase-1 processing in the human lung tissue from silicosis patients, which is not consistent with human BALF and mice data." (PMID 36459518, 2022). "Though the Nlrp3 inflammasome is involved in silicosis pathogenesis, inhibition of its classic downstream factors, Caspase-1 and Gsdmd, fails to block pyroptosis and cytokine release." (PMID 36459518, 2022). "Finally, we found that inhibitors of Caspase-1, -3, -8 or an FDA approved drug, dimethyl fumarate, could dramatically alleviate silicosis pathology through blocking cleavage of Gsdmd and Gsdme." (PMID 36459518, 2022). "Pulmonary inflammation in the context of silicosis is also maintained by non-immune cells and silica exposure leads also to upregulation of NLRP3 inflammasome-caspase-1 activation in lung epithelium." (PMID 35130879, 2022). "The contribution of inflammasome activation to the development of silicosis has been shown in a mouse model; however caspase-1 activity and its particle surface reactivity dependency in the BALF of rats was not demonstrated yet, neither has it been localized in an animal model of silicosis." (PMID 25406505, 2014).
cognitive decline (11 papers, 2020 to 2025). "We do know that overexpression of caspase-1, caspase-2, caspase-3, caspase-6, and caspase-8 is linked to Aβ accumulation and cognitive decline in mouse models and patients with neurodegenerative diseases." (PMID 39625520, 2024). "In line with our results, a recent study showed that administration of a caspase-1 inhibitor to pre-symptomatic APP mutant mice slowed down cognitive decline." (PMID 38230736, 2024). "However, before the typical AD onset, the detailed mechanism by which Caspase-1-dependent inflammation leads to cognitive decline remains undefined." (PMID 35172755, 2022). "The cognitive decline in the aging process is regulated by the increased expression of caspase-1, a protein that regulates the maturation and secretion of interleukin (IL)-1β and IL-18, and decreased expression of BDNF, a protein that improves synaptic connectivity." (PMID 34526890, 2021). "Studies in rodents lacking NLRP3 or caspase-1 have shown protection from neuroinflammation and cognitive decline." (PMID 39125762, 2024).
endometrial cancer (11 papers, 2020 to 2025). Primary or metastatic malignant neoplasm involving the endometrium (mucous membrane that lines the endometrial cavity). "Moreover, NLRP10 is associated with a poor prognosis in endometrial cancer by inhibiting NF-κB activation and apoptosis, along with caspase-1-mediated IL-1β maturation." (PMID 40124684, 2025). "Estrogen-related receptor alpha (ERRα), a central regulator of cellular energy metabolism linked to poor cancer prognosis, enhances glycolytic metabolism and targets the NLRP3/caspase-1/GSDMD pathway to regulate pyroptosis in endometrial cancer." (PMID 40718836, 2025). "Our study identified cleaved caspase-1 p20 as an independent predictor of adverse outcomes in endometrial cancer." (PMID 38562170, 2024). "A recent study demonstrated that hydrogen inhibited the growth of endometrial cancer through the pyroptosis pathway mediated by ROS/NLRP3/caspase-1/GSDMD, indicating there is a close relationship between pyroptosis and EC." (PMID 35299842, 2022). "In contrast, overexpression of NLRP3 enhances the activities of proliferation, migration and invasion as well as increasing caspase-1 activation and IL-1β secretion in human endometrial cancer cells." (PMID 33613533, 2020). "In the present study, we found that the NLRP3 inflammasome (including NLRP3 and caspase-1 expression) was upregulated in endometrial cancer tissue compared to that of benign tissues." (PMID 31924176, 2020). "This theoretical perspective offers valuable insights into reconciling the divergent prognostic implications of high cleaved caspase-1 p20, which indicates a worse prognosis, with the more favorable outlook associated with high cleaved gasdermin D and low CHMP4B expressions in endometrial cancer." (PMID 38562170, 2024). "Immunohistochemistry was used to assess the expression of four pyroptosis-associated molecules (NLRP3, cleaved caspase-1 p20, cleaved gasdermin D, and CHMP4B) in 351 patients with endometrial cancer, and their associations with clinical, pathological, and survival outcomes were analyzed." (PMID 38562170, 2024). "Although the prognostic impact of caspase-1 (CASP1) has not been previously evaluated in endometrial cancer, diverse associations have been reported between this molecule and prognosis in other cancer types." (PMID 38562170, 2024). "Accordingly, our findings showed that cleaved caspase-1 p20, an effector protein within the inflammasome of the canonical pyroptosis pathway, was independently associated with adverse RFS and OS when highly expressed in endometrial cancer." (PMID 38562170, 2024). "Silencing NLPR3 inhibited tumor growth in a nude mouse endometrial tumor model, cell proliferation, migration, and invasion and reduced expression of IL-1β and caspase-1, while overexpression of NLPR3 led to the opposite results in endometrial cancer." (PMID 34239588, 2021). "In the present study, we explored the effects of hydrogen on endometrial cancer and provided the first evidence that hydrogen induces pyroptosis via ROS-NLRP3-caspase-1 pathways." (PMID 31924176, 2020). "We observed overexpression of NLRP3, caspase-1, and GSDMD in human endometrial cancer and cell lines by IHC and western immunoblotting." (PMID 31924176, 2020). "We observed over-expression of NLRP3, ASC, pro-caspase-1, caspase-1, and GSDMD in Ishikawa and HEC1A endometrial cancer cell lines in contrast to endometrial epithelial cells." (PMID 31924176, 2020). "We performed immunohistochemical staining and western immunoblotting analysis to observe expression of NLRP3, caspase-1, and GSDMD in human and xenograft mice endometrial cancer tissue and cell lines." (PMID 31924176, 2020). "We observed LDH and IL-1β release to be increased in hydrogen-treated endometrial cancer cells that were upregulated by LPS and nigericin or downregulated by ROS, NLRP3, or the caspase-1 inhibitor." (PMID 31924176, 2020).